CASP9 (caspase 9)
Diseases named in the same sentence as CASP9 in open-access papers (continued):
Sharing a sentence is not in itself a finding about the gene and the disease.
cancer (continued). "Thus, we sought to determine whether increased PTEN in aloperine-treated cancer cells reduced the levels of p-AKT and activated caspase-9." (PMID 25886453, 2015). "Similarly, active caspase-9, a caspase frequently activated by anti-cancer agents, was also not detected in A498 cells treated with EA (data not shown)." (PMID 23958461, 2013). "Additionally, PF10 suppressed the proliferation of cancer cell lines, with IC50 values ranging from 2.0 to 2.5 μg/mL, and induced apoptosis, as evidenced by Poly (ADP-ribose) polymerase (PARP) cleavage, activation of caspase 3 and caspase 9 and Bax protein accumulation." (PMID 41369859, 2025). "Hence, SI might have an anti-cancer effect by regulating BAD, caspase-9, Bcl-2, and eNOS." (PMID 34248628, 2021). "It was also found that treatment of cancer cells with a caspase-8 inhibitor significantly suppressed C5-induced apoptosis; however, treatment with caspase-9 inhibitors did not affect C5-induced apoptosis, suggesting that C5 may induce apoptosis via the extrinsic pathway by activating caspase-8." (PMID 32075108, 2020). "In addition, no apparent activation of intrinsic apoptosis signaling protein caspase-9 and extrinsic apoptosis signaling protein caspase-8 were observed after Ching001 treatment (data not shown), suggesting that Ching001 induced cancer cell apoptosis is via ER stress." (PMID 23646116, 2013). "Furthermore, in a Cancer Pathway Finder RT2 PCR array study (SA Biosciences) (data not shown) significant increases in the expression of the CASP9 and FASLG genes in response to S. frutescens extract indicate that the extract may induce apoptosis via the intrinsic as well as extrinsic pathways." (PMID 27656236, 2016). "SKBR3 grown under 3D static conditions exhibited CASP3 levels that were not consistent with CASP9, this may reflect the inherent heterogeneity of the multi-clonal SKBR3 cancer cell line." (PMID 32694700, 2020). "In Pcys-treated gut cell lines, caspase 8 (apoptosis extrinsic pathway) but not caspase 9 (apoptosis intrinsic pathway) is activated after 3 hours through P38 phosphorylation (90 min), emphasizing the potency of lowbush blueberry Pcys to eradicate gut TRAIL-resistant cancer cells." (PMID 26180579, 2015).
tumor (501 papers, 2001 to 2025). "Following 48 h of exposure, the tumor cells were analyzed for the expression of apoptosis and proliferation markers, such as Caspase-9 and Ki-67, as well as markers associated with cisplatin resistance, including APEX1, MTDH, ERK1, and STAT3." (PMID 40149331, 2025). "AKT promotes tumor cell survival by phosphorylating pro-apoptotic proteins, such as Bcl-2-associated death promoter and Caspase-9, thereby enhancing the cells’ ability to evade apoptosis, and it also plays a crucial role in tumor invasion and metastasis." (PMID 40141978, 2025). "The antitumor action, besides being related to the inhibition of PG production, is also associated with the activation of caspase-3 and caspase-9, induction of tumor cell apoptosis, inhibition of tumor cell proliferation, and anti-angiogenesis." (PMID 38974039, 2024). "To investigate the relevance of caspase-9 activity in TNFSF sensitization in PRKCSH-deficient cells, we investigated the effect of a caspase-9 inhibitor on tumor sphere formation." (PMID 38200153, 2024). "The results showed that supernatant of M1-iBMDMs promoted the expression of apoptosis associated genes, including APAF1 and Caspase-9 in tumor cells, and decreased the level of protective molecule BCL2." (PMID 38650937, 2024). "Based on the available research, TanIIA have a particular ability to reduce mitochondrial potential in tumor cells, causing the increase of mitochondrial ROS production and activation of the caspase-9 mitochondrial apoptosis pathway." (PMID 39544939, 2024). "An adaptive tumor immune resistance to CD47 immunotherapy is reported via suppressing radiation-associated tumor immunogenicity by hijacking caspase 9 signaling pathway." (PMID 35314680, 2022). "CASP9 is a protein-coding gene, and many reports have shown that CASP9 gene polymorphisms are associated with increased tumor risk, but this conclusion is controversial." (PMID 35845137, 2022). "PTEN and p-AKT are associated with cell apoptosis, and play a crucial role in tumor progression, so the mRNA level of the Caspase-9, Caspase-3, Bcl-2 and Bax, which are considered as the dominant role during apoptosis, were detected by qRT-PCR." (PMID 31666604, 2019). "Loss of Apaf-1 expression can aid tumour cells in evading immune attack-induced death and/or Caspase-9 mediated apoptosis, resulting in metastasis." (PMID 28479926, 2017). "The increased Bax and decreased Bcl-2 in the tumor lysates from chaetocin-treated mice were also observed with the activation of caspase-9/-3, which is closely associated with chaetocin-induced apoptosis." (PMID 28419143, 2017). "Both cisplatin and doxorubicin suppressed tumor cells by activating P21-associated cell cycle arrest and caspase-3 dependent apoptosis via caspase-8 or caspase-9 pathways." (PMID 26557666, 2015). "Our results showing changed ratios of proapoptotic [9a] and antiapoptotic [9b] Caspase-9 splice variants in tumor tissue samples resemble those found for survivin, a member of the inhibitor of apoptosis protein (IAP) family." (PMID 21082031, 2010). "Furthermore, the changes in apoptosis-related proteins and cell cycle-associated proteins, including PUMA, Bcl-2, Bax, Caspase-9, p21, and Cyclin D1, in the tumor tissues were consistent with the in vitro results." (PMID 35759135, 2022). "Furthermore, AAV6 serotype vectors encoding an inducible caspase 9 suicide gene, packaged in the presence of miR‐636, showed a significant tumor regression (~2.2‐fold, P < .01) in a syngeneic murine model of T‐cell lymphoma." (PMID 32108448, 2020). "Indeed, survivin is a tumor specific molecule, which inhibits caspase-9 activation and causes prevention of apoptosis." (PMID 30034311, 2018).
tumor (continued). "The CASP9 gene encodes for a protein whose function is comparable to a tumor suppressor and its functional polymorphisms may be responsible for alterations in proliferation." (PMID 30075788, 2018). "Administration of nimbolide after 8 weeks of DMBA painting arrested tumor growth associated with induction of apoptosis and inhibition of autophagy as evidenced by a significant increase in Bax and cleaved caspase-9 and -3 with downregulation of Bcl-2, Beclin, ATG5, and LC-3." (PMID 30352996, 2018). "In conclusion, the CASP9 rs4645981 polymorphism, CASP3 and CASP9 haplotypes may be useful prognosis markers for HCC patients with surgical resection of tumor." (PMID 28453560, 2017). "We postulate that TH causes the up-regulation of Apaf-1 and Caspase-9 expression and may activate the intrinsic apoptotic pathway to modulate tumor growth." (PMID 28399853, 2017). "It has been reported that inhibition of PI3K/Akt signaling pathway led to radiosensitize the tumor cell by affecting repair of DNA double-strand breaks via DNA-PKcs, and this pathway inactivates Bad and caspase-9 and activates p21, p27 and Mre11, which are associated with cellular radiosensitivity." (PMID 23777562, 2013). "Interestingly, the activation of caspase-3 is tightly linked to the activation of caspase-9 in these anti-tumor studies." (PMID 22363243, 2011). "Therefore, revealing the mechanism by which Dronc expression in EBs maintains tissue homeostasis may also have important implications for understanding of the tumor-promoting effect of loss of caspase-9 in humans." (PMID 33514791, 2021). "In contrast to that in the tumor adjacent normal tissue, the expression levels of cleaved caspase-3, caspase-3, caspase-8 and caspase-9 were significantly higher in tumor tissues (all p<0.001, Wilcoxon signed-rank test), suggesting that these caspases might be associated with tumor transformation." (PMID 28700659, 2017). "It is possible that the associated stresses of in vivo tumor growth (e.g. hypoxia) generate a death signal (activated caspases) that is sufficient to render the tumor cells sensitive to inhibition of XIAP solely via the disruption of the caspase 9/XIAP interaction." (PMID 20067634, 2010). "Caspase-9 is involved in caspase-dependent apoptosis, whereas Ki-67 is a marker of tumor cell proliferation." (PMID 40149331, 2025). "Nevertheless, olympiforin A, HF and other PPAPs have been reported to either induce apoptosis or activate caspase 9 in tumor cell lines." (PMID 41155703, 2025). "A comprehensive examination of IHC staining of HE, Ki-67, caspase-3, and caspase-9 positive cells within the tumor tissues revealed a substantial decrease in cell proliferation and a concomitant increase in apoptosis in the treated group." (PMID 40755756, 2025). "Our findings confirm the well-established relationship between STAT3 and tumor cell death, specifically through caspase-3 and caspase-9 activation." (PMID 40217305, 2025). "Pseudotime trajectory analysis revealed a progressive increase in CASP9 expression along the developmental axis of malignant cell differentiation, consistent with its enrichment in late-stage or more aggressive tumor subsets." (PMID 41201629, 2025). "We evaluated in B cells the efficacy of inserting the inducible caspase-9 (iCasp9) suicide gene, together with either a reporter gene or a single-chain immunoglobulin cassette specific for a tumor antigen." (PMID 41438137, 2025). "CASP9 acts as both a genetic driver and spatial regulator of tumor–macrophage interactions, contributing to disease progression." (PMID 41201629, 2025). "These compounds can effectively decrease tumour cell survival by activating initiator caspase 3/7, and executive caspase-8 and caspase-9." (PMID 41198778, 2025).
tumor (continued). "B63, a synthetic Curcumin analog, induces ER Ca2+ depletion, leading to UPR activation and apoptosis via caspase-3 and caspase-9 activation, ultimately inhibiting tumor growth." (PMID 41476609, 2025). "It enhances the cleaved expression of Caspase-9, reduces the production of bcl-2, induces tumor cell apoptosis, and decreases the expression of vascular endothelial growth factor to reduce tumor angiogenesis." (PMID 40584613, 2025). "Activated Akt exerts its effects by stimulating the downstream mTOR pathway or by inhibiting proteins such as Bad and Caspase-9, which regulate cell proliferation, differentiation, apoptosis, and migration, contributing to radiation resistance in tumor cells." (PMID 41178971, 2025). "A five-gene apoptosis-related signature derived from CASP9-stratified tumor cells robustly predicted patient survival across both training and validation cohorts." (PMID 41201629, 2025). "By constructing a robust prognostic model based on differentially expressed genes between CASP9-high and CASP9-low tumor cells, we demonstrated its strong predictive performance." (PMID 41201629, 2025). "Apoptosis-high tumor cells, characterized by elevated CASP9 expression, preferentially localized near macrophage-enriched stromal regions and exhibited stronger spatial clustering." (PMID 41201629, 2025). "The markers for the intrinsic apoptotic pathway, Bax, cleaved caspase-3, and cleaved caspase-9, were significantly elevated in the tumour samples from treated mice compared to those from untreated controls." (PMID 40244003, 2025). "This unique localization pattern supports CASP9 as a central mediator of tumor–macrophage interactions in ccRCC." (PMID 41201629, 2025). "The results demonstrated that BAG2 KO significantly augmented the protein expression of caspase-3 and caspase-9 in tumor tissues compared with controls." (PMID 40755756, 2025). "The CASP9 expression level was higher in the normal tissue than the tumor tissue in UCEC and COAD patients." (PMID 38542508, 2024). "Research has shown that baicalein mainly affects the levels of cytochrome C, Caspase-3, Bcl-2 family of proteins, Caspase-9, and others through various signaling pathways to affect endogenous apoptosis of the tumor cells." (PMID 39144617, 2024). "The tumor size is decreased and the death of tumor cells is encouraged by this complex carbohydrate, possibly by activating caspase-3 and caspase-9." (PMID 38420194, 2024). "The CASP9 gene expression level was higher in the normal tissue than the tumor tissue in UCEC and COAD patients." (PMID 38542508, 2024). "Mice treated with P. crinita free extract (25, 50 mg/kg), exposed a significant improvement in the caspase 9 gene expression (40%, and 60%, respectively) related to a tumor control group." (PMID 38469406, 2024). "The results showed that the expression levels of cleaved PARP, Bax, and cleaved Caspase 9 increased in both tumor cells after lumbrokinase treatment, while the expression level of Bcl-2 decreased accordingly." (PMID 39062456, 2024). "The PRKCSH-IGF1R axis in tumor cells impairs caspase-8 activation, increases Mcl-1 expression, and inhibits caspase-9, leading to an imbalance between cell death and survival." (PMID 38200153, 2024).
tumor (continued). "Glabridin induces tumor cell apoptosis by upregulating caspase-3, caspase-8, caspase-9 cleavage while enhancing autophagy by upregulating LC3-II and beclin-1." (PMID 39723390, 2024). "Caspase-9 inhibition restored the TRAIL-mediated reduction in tumor sphere size and strongly suppressed TRAIL-mediated cell death and caspase-9 activation in PRKCSH-deficient cells." (PMID 38200153, 2024). "Elevated acidity impedes enzymes pivotal for apoptosis initiation, such as caspase-3, caspase-9, and caspase-8, ultimately facilitating cell survival and tumor progression." (PMID 39494260, 2024). "Abolishing ICAM-1–FGG interaction induces NSCLC cell death by activating caspase-9/3 and significantly inhibits tumor development in a mouse xenograft model." (PMID 39168965, 2024). "For example, CASP9 inhibition triggers immunogenic cell death, increases tumor-intrinsic innate sensing, and induces remarkable anti-tumor effects in chemotherapy-induced anti-tumor immunity." (PMID 38678251, 2024). "Caspase-9 activation subsequently initiates a cascade of caspase-dependent apoptosis, leading to tumor cell death." (PMID 39795861, 2024). "Consistent with tumour suppressors being a major target of DOWN-paSNVs, genes with this type of mutations were significantly enriched for apoptosis-related functions (e.g. tumour suppressors CASP9 or FHIT)." (PMID 39660592, 2024). "H&E and IHC staining demonstrated necrosis and upregulated expression of cleaved Caspase 3 and Caspase 9 in the xenograft tumor of U87-CHIP cells following temozolomide administration." (PMID 39075053, 2024). "Seven genes passing these filters were involved in various aspects of tumour biology, including cell survival and DNA repair (CASP9, NDRG1, and XPA), mTOR signalling (TSC1), and transcription and RNA processing (ETV6, ISY1, and SMAD2)." (PMID 39660592, 2024). "When HINT1 is overexpressed in SW480 and McF-7 tumor cells, it leads to a decrease in Bcl-2 levels, an increase in Bax levels, and elevated expression of caspase-9, caspase-8, and caspase-3, ultimately resulting in the induction of apoptosis in tumor cells." (PMID 38068718, 2023). "They found that gentian glycosides inhibited tumor cell proliferation and induced apoptosis by regulating the Bax/Caspase-9/Caspase-3 cell pathway." (PMID 37397486, 2023). "In vivo, combination treatment induced a significant antitumor effect with an obvious regression in tumor size and a remarkable and significant expression of caspase-3, caspase-8, and caspase-9 compared to monotherapies." (PMID 37720338, 2023). "It was found that naringenin can not only activate the caspase-9/caspase-3/PARP/C-PARP apoptosis pathway but also inhibit tumor cell proliferation and growth via the inhibition of JAK-2/STAT-3." (PMID 37298981, 2023). "Caspase-3, caspase-8, and caspase-9 expression were evaluated in tumor specimens by immunohistochemistry assays to assess apoptosis in treated and control groups." (PMID 37720338, 2023). "They found that the gene therapy led to significant overexpression of apoptotic protease activation factor-1, caspase 3 and caspase 9 in A2780ADR drug-resistant tumor cells." (PMID 37612696, 2023). "As expected, our gene expression results demonstrated that the triple-drug combination (TME) significantly reduced the levels of BCL2 and enhanced the expression levels of BAX, BAD, caspase-9, 8 and 3 when compared to that of tumor-control group (p < 0.0001)." (PMID 37025487, 2023). "The results showed a significant 2.7-fold increase in the activity of caspase-3 and a 1.9-fold increase in the activity of caspase-9, suggesting that nHAp can trigger the activation of caspase-3 and caspase-9 in tumor cells." (PMID 37091350, 2023).